RASGRP1 (RAS guanyl releasing protein 1)
Description:
Functions as a calcium- and diacylglycerol (DAG)-regulated nucleotide exchange factor specifically activating Ras through the exchange of bound GDP for GTP. Activates the Erk/MAP kinase cascade. Regulates T-cell/B-cell development, homeostasis and differentiation by coupling T-lymphocyte/B-lymphocyte antigen receptors to Ras. Regulates NK cell cytotoxicity and ITAM-dependent cytokine production by activation of Ras-mediated ERK and JNK pathways. Functions in mast cell degranulation and cytokine secretion, regulating FcERI-evoked allergic responses. May also function in differentiation of other cell types.
Synonyms: CalDAG-GEFII; RASGRP; CALDAG-GEFI; IMD64
Tractability: Small molecule: a high-quality ligand is known. Antibody: its Gene Ontology location is reachable by antibodies, with high confidence; UniProt places it where antibodies can reach, with medium confidence; the Human Protein Atlas places it where antibodies can reach. PROTAC: ubiquitination databases record sites on it; a small molecule that binds it is known.
Target class: Other cytosolic protein
Gene: Protein-coding gene on chromosome 15 (38,488,103 to 38,565,575, reverse strand). Ensembl gene ENSG00000172575.
Subcellular location: Cytoplasm, cytosol; Cell membrane; Golgi apparatus membrane; Endoplasmic reticulum membrane
Subcellular location (Human Protein Atlas): Cytosol; Plasma membrane
Pathways (Reactome):
Immune System: Activation of RAS in B cells; FCERI mediated NF-kB activation; Rap1 signalling
Signal Transduction: Integrin signaling; RAF/MAP kinase cascade
Hemostasis: Effects of PIP2 hydrolysis
Gene Ontology:
Molecular function: calcium ion binding; diacylglycerol binding; guanyl-nucleotide exchange factor activity; identical protein binding; phosphatidylcholine binding; zinc ion binding; lipid binding; GTPase regulator activity
Biological process: activation of GTPase activity; B cell activation; B cell proliferation; natural killer cell activation; positive regulation of MAP kinase activity; positive regulation of natural killer cell mediated cytotoxicity; positive regulation of protein phosphorylation; positive regulation of Ras protein signal transduction; regulation of ERK1 and ERK2 cascade; T cell activation; T cell proliferation; Ras protein signal transduction; signal transduction; leukocyte activation; positive regulation of immune system process; positive regulation of natural killer cell activation; positive regulation of natural killer cell differentiation; positive regulation of T cell differentiation in thymus; regulation of intracellular signal transduction; small GTPase-mediated signal transduction
Cellular component: cytosol; Golgi apparatus; plasma membrane; membrane; endoplasmic reticulum membrane; Golgi membrane
Genetic constraint (gnomAD): Loss-of-function variants: 32 observed, 79.86 expected, observed/expected ratio (o/e) 0.4, 90% interval 0.3 to 0.54. The upper end of that interval is the gene's LOEUF score, 0.54, which puts it in group 2 of 6, group 1 being the genes least tolerant of losing a copy. Missense variants: 667 observed, 918.27 expected, observed/expected ratio (o/e) 0.73, 90% interval 0.68 to 0.77. Synonymous variants: 313 observed, 339.96 expected, observed/expected ratio (o/e) 0.92, 90% interval 0.84 to 1.01.
Gene-disease validity (ClinGen):
ClinGen rates the evidence that RASGRP1 causes each of these diseases.
immunodeficiency 64 (autosomal recessive): Definitive.
Homologues: Orthologues: chimpanzee RASGRP1 (99% identical), macaque RASGRP1 (97% identical), rabbit RASGRP1 (95% identical), guinea pig RASGRP1 (95% identical), pig RASGRP1 (94% identical), dog RASGRP1 (94% identical), mouse Rasgrp1 (90% identical), rat Rasgrp1 (85% identical), tropical clawed frog rasgrp1 (71% identical). Paralogues in human: RASGRP3 (45% identical), RASGRP4 (38% identical), RASGRP2 (33% identical), RAPGEF2 (20% identical), RAPGEF6 (19% identical), SOS2 (17% identical), SOS1 (17% identical), RALGPS2 (15% identical), RALGDS (14% identical), RALGPS1 (13% identical), RGL2 (13% identical), RASGRF1 (12% identical), and 12 more.
Diseases named in the same sentence as RASGRP1 in open-access papers:
RASGRP1 is named in the same sentence as 83 diseases in open-access papers, as found by Europe PMC text mining. Sharing a sentence is not in itself a finding about the gene and the disease. The quoted sentences say what the papers report.
lupus (13 papers, 2012 to 2023). "Taken together, we have identified and mechanistically dissected a lupus risk locus in the 2nd intron of RASGRP1, which regulates T- and B-cell development and the MAP kinase pathway." (PMID 31164884, 2019). "MiR-21 affects indirectly DNA methyltransferase 1 (DNMT1) expression in a lupus-prone murine model, by targeting RAS guanyl releasing protein 1 (RASGRP1), linked to autoimmune disease." (PMID 30322050, 2018). "Both RGS1 and RASGRP1 variants associated with systemic lupus erythematosus, Crohn’s disease, rheumatoid arthritis, multiple sclerosis, blood pressure, type 1 diabetes, type 2 diabetes, urinary metabolites and response to chemotherapy." (PMID 27804980, 2016). "With these biochemical and cellular experiments in mind, it is interesting to speculate on how the regulation of various of the Lupus-associated RasGRP1 mRNA splice variants that lack portions of the EF hands may be altered." (PMID 24027568, 2013). "In accordance with the idea that RasGRP1 regulates autoimmunity in mice, a study analyzing a cohort of patients with systemic lupus erythematosus (SLE) discovered 13 new splice variants of RasGRP1 transcripts, resulting in diminished RasGRP1 activity in these patients." (PMID 22719950, 2012). "Furthermore, several genetics studies have linked single nucleotide polymorphisms (SNPs) in RasGRP1 to human autoimmune disease, and low RasGRP1 levels have been detected in T lymphocytes from patients with Systemic Lupus Erythematosus (SLE), and rheumatoid arthritis (RA)." (PMID 28952923, 2017). "Increased miR-21 expression in CD4+ T cells from both lupus patients and lupus-prone MRL/lpr mice promoted cell hypomethylation by repressing RAS guanyl-releasing protein 1 (RASGRP1) expression." (PMID 27271606, 2016). "The other data available on RasGRP1 and RasGRP3 are derived from experimental studies in mice, from cell lines and from systemic lupus erythematosus (SLE) T cells." (PMID 26714738, 2015). "RASGRP1 splice variants have been documented for patients with systemic lupus erythematosus (SLE)." (PMID 24027568, 2013). "Another study examining microRNA expression in lupus CD4+ T cells reveals that RasGRP1 can be targeted by miR-21, ultimately contributing to the DNA hypomethylation seen in patients with SLE." (PMID 22719950, 2012). "Neutrophil degranulation was the most significantly enriched pathway in this signature, whereas gene network analysis revealed that the lupus-susceptibility risk loci NCF2, ITGAM, NCF1, RASGRP1 and FCGR2A33–35 were high-degree hub genes, suggesting their central pathogenic role in LN." (PMID 35906002, 2022). "Indeed, RasGRP1-/- mice become autoimmune-prone and develop a lupus-like phenotype." (PMID 26714738, 2015). "While not emphasized in this focused review, progress in RasGRP1 research is also being made in the areas of schizophrenia, neuro-inflammation, systemic lupus erythematosus, Parkinson’s disease, and angiogenesis." (PMID 36675167, 2023).
Autoimmunity (12 papers, 2011 to 2023). The occurrence of an immune reaction against the organism's own cells or tissues. "In humans, RasGRP1 deficiency may interfere with T-cell and B-cell proliferation and activation, thereby causing various autoimmune disorders." (PMID 34484216, 2021). "RASGRP1 is mainly expressed in T cells and thymocytes, which can prevent virus infection and autoimmunity-related activated T cell proliferation." (PMID 37426642, 2023). "It is believed that aberrant expression of RASGRP1 plays an important part in the development of autoimmunity." (PMID 36619718, 2022). "While autoimmunity in RasGRP1−/− mice has been demonstrated previously, a conflicting report proposes that those results stem from the mixed background of the mice analyzed." (PMID 22719950, 2012). "From our results, we concluded that the deletion or truncation of RasGRP1 protein impaired thymic selection and/or T cell homeostasis such that these mice indeed developed an autoimmune disorder." (PMID 22719950, 2012). "Additional evidence supporting our claim that the tail domain is essential for RasGRP1 function came from our assessment of T cell function and autoimmunity in RasGRP1d/d mice." (PMID 22719950, 2012). "Previous studies have emphasized the importance of RasGRP1 in the positive selection of thymocytes, activation of T cells, and control of autoimmunity." (PMID 22719950, 2012). "By promoting lymphocyte proliferation, RASGRP1 activity is also indispensable to autoimmunity." (PMID 37026010, 2023). "For instance, RASGRP1-dependent downregulation of DNA methyltransferase promotes CD4+ T cell hypomethylation, followed by induction of methylation-sensitive genes which are associated with autoimmunity." (PMID 31948396, 2020). "Along these lines, RASGRP1-deficient mice developed autoimmune LPD resembling systemic lupus erythematous when getting older and RASGRP1 is considered as a risk locus for autoimmunity." (PMID 29942301, 2018). "Therefore, RasGRP1 inhibition promotes autoimmunity via activation of B cells by autoreactive CD4+ T cells, while RasGRP3 inhibition renders B cells less sensitive to T cell signals." (PMID 26714738, 2015). "Therefore, understanding the regulation of RasGRP1 and its role in Erk activation is essential to comprehend the establishment of T cell tolerance, autoimmunity, and transformation." (PMID 22719950, 2012). "Interestingly, RasGRP1−/− mice develop an autoimmune disorder marked by splenomegaly and auto-antibody production." (PMID 22719950, 2012). "Also, two SLE patients have T cells containing very little, if any, RasGRP1 protein, supporting a role for RasGRP1 in the onset of autoimmunity." (PMID 22719950, 2012). "Indeed, this study demonstrated that RasGRP1 inhibition instigates the emergence of autoimmunity." (PMID 26714738, 2015). "Finally, our observations also support the design of specific inhibitors of RASGRP1 that could provide a potential way to suppress abnormal proliferation of activated T cells occurring in various pathophysiological conditions including autoimmunity." (PMID 29282224, 2018). "Moreover, in patients with autoimmunity, CD4+ T cells exhibited reduced RUNX1 and RASGRP1 expression, which was correlated to active inflammation." (PMID 37670378, 2023). "In addition, double mutant mice RasGRP1-/-RasGRP3-/- do not develop signs of autoimmunity contrary to RasGRP1-/- mice." (PMID 26714738, 2015).
autoimmune disease (10 papers, 2013 to 2025). A disorder resulting from loss of function or tissue destruction of an organ or multiple organs, arising from humoral or cellular immune responses of the individual to their own tissue constituents. "For example, variants near a gene called Rasgrp1 have been linked to two autoimmune diseases – type 1 diabetes and Graves’ disease—in which the immune system mistakenly attacks the body’s own cells and tissues." (PMID 24336796, 2013). "More recently, RasGRP proteins, particularly RasGRP1, have also been associated with human diseases such as autoimmune disease and cancer." (PMID 24027568, 2013). "Furthermore, one study found that the binding of RUNX1 to a putative autoimmunity-associated enhancer 1 upstream of Rasgrp1 mediates the RasGRP1 deficiency-mediated autoimmune disease." (PMID 36675167, 2023). "We propose that Rasgrp1Anaef mice may provide a useful model system for further studies to help elucidate how RASGRP1 variants contribute to autoimmune disease, and to help target future efforts to modulate this pathway pharmacologically." (PMID 24336796, 2013). "RasGRP1 has been identified as a candidate risk gene for SCZ and autoimmune disease, therefore representing a possible point of convergence between mechanisms involving the nervous and the immune system." (PMID 35204828, 2022). "RasGRP1 is important in some cancers and autoimmune diseases but, in contrast to SOS, its regulatory mechanisms are poorly understood." (PMID 23908768, 2013). "Likewise, in RASGRP1-deficient mice development of CD4 Treg cells in the thymus is severely impaired, and loss-of-function mutations of RASGRP1 was identified in autoimmune diseases." (PMID 31948396, 2020). "Recently, the potential role of RASGRP1 in development of autoimmune diseases was reported." (PMID 31948396, 2020). "RASGRP1 is crucial for T cell signaling, impacting the MAPK/ERK pathway, and its dysregulation can lead to immune imbalances in autoimmune diseases." (PMID 41212883, 2025).
colorectal cancer (8 papers, 2020 to 2025). A primary or metastatic malignant neoplasm that affects the colon or rectum. "As a predictive biomarker for EGFR inhibitors in colorectal cancer, RasGRP1 has been linked to several cancer-related processes, such as hepatocarcinoma carcinogenesis and displaying an association with improved overall survival in breast cancer." (PMID 39950162, 2025). "A recent study reported that upregulation of RasGRP1 expression is associated with a better prognosis in colorectal cancer patients because it inhibits proliferative EGFR-SOS1-Ras-ERK signalling." (PMID 36385095, 2022). "Previous studies have reported that RASGRP1 plays an oncogenic role in several cancers, including leukemia, lymphoma, skin tumors, and colorectal cancer." (PMID 38773970, 2024). "Many studies have shown that RASGRP1 played an important role in the development of various cancers including BC, squamous cell carcinoma, colorectal cancer, hepatocellular carcinoma, as well as lymphoma and leukemia." (PMID 37520534, 2023). "The structure, function, and regulation of RasGRP1 are briefly discussed, and the role of RasGRP1 in leukemia, lymphoma, squamous cell carcinoma, colorectal cancer, hepatocellular carcinoma, and breast cancer are reviewed in-depth below." (PMID 36675167, 2023). "RASGRP1 is a unique biomarker for colorectal cancer and is located in the EGFR pathway." (PMID 40861815, 2025). "Surprisingly, RasGRP1 acts as a tumor suppressor in colonic epithelium; furthermore, RasGRP1 can be used as a biomarker for predicting the efficacy of anti-epidermal growth factor receptor (EGFR) therapy for CRC (colorectal cancer) patients." (PMID 36675167, 2023).
diabetes (7 papers, 2019 to 2025). "Studies have shown that RASGRP1 was potently associated with the onset of type 2 diabetes mellitus (T2DM), and RASGRP1 rs7403531 was significantly correlated with islet function in T2DM patients." (PMID 38730425, 2024). "In both T1D and T2D, we found enrichment of monogenic forms of diabetes, as expected —2 genes in T1D (RASGRP1, INS) and 8 in T2D (HNF1B, GCK, WFS1, KCNJ11, ABCC8, HNF1A, PPARG, SLC2A2)." (PMID 33836063, 2021). "Recent studies have shown that multiple single nucleotide polymorphisms (SNPs) in RASGRP1 gene were related to type 2 diabetes mellitus (T2DM), suggesting that RASGRP1 may drive the process of T1DM through immunity, but whether it is also through a similar possible mechanism for T2DM is unclear." (PMID 38730425, 2024).
leukemia (7 papers, 2013 to 2024). A malignant (clonal) hematologic disorder, involving hematopoietic stem cells and characterized by the presence of primitive or atypical myeloid or lymphoid cells in the bone marrow and the blood. "Rasgrp1, which encodes a guanine nucleotide exchange factor that promotes Ras activation, is a recurrent site of retroviral integrations in KrasWT leukemias." (PMID 31199785, 2019). "Transgenic over-expression of RasGRP1 in developing T lymphocytes causes thymic lymphomas in mice and several unbiased mouse model screens for leukemia genes have identified the RasGRP1 locus as a hot-spot for leukemia virus integrations driving blood cancer (112, –114)." (PMID 24027568, 2013). "This is consistent with the finding from a later study that identified RasGRP1 as a negative regulator of Ras signaling in Kras−/− NrasQ61R/+-driven leukemia." (PMID 36675167, 2023). "In this review, we outline the structure, function, and regulation of RasGRP1 and focus on the existing knowledge of the role of RasGRP1 in leukemia and other cancers." (PMID 36675167, 2023). "In contrast, Syk and Rasgrp1 are increased in DKO compared to E2A-/- leukemias but decreased after deletion of Lef1 from E2a-/-Lef1F/F leukemias." (PMID 35371057, 2022). "Regulation occurs most definitely at the level of RasGRP1 expression since dysregulated expression of a wild-type RasGRP1 form results in leukemia." (PMID 24027568, 2013). "Additionally, leukemia driven by the overexpression of RasGRP1 and K-RasG12D are mutually exclusive and represent the distinct mechanisms of leukemogenesis." (PMID 36675167, 2023). "This has identified RasGRP1 and its regulators as promising targets in leukemia and other cancers." (PMID 36675167, 2023). "Thus, we could speculate that Syk and Rasgrp1 are positively regulated by LEF1 or TCF1, gaining a dependence on high levels of LEF1 in E2a-/-Lef1F/F leukemias and TCF1 in DKO leukemias." (PMID 35371057, 2022).
lymphoma (7 papers, 2005 to 2024). A malignant (clonal) proliferation of B- lymphocytes or T- lymphocytes which involves the lymph nodes, bone marrow and/or extranodal sites. "The overexpression of RasGRP1 alone is insufficient for lymphoma- or leukemo-genesis." (PMID 36675167, 2023). "RASGRP1-deficient patients commonly show recurrent infections, inverted CD4+: CD8+ T cell ratio, poor T cell proliferation, defective NK cell function, autoimmunity, and EBV-associated lymphoma." (PMID 34638238, 2021). "In another study, the interactions between RASGRP1 and the RAS effector kinase CRAF was found to be an important factor that led to drug resistance in lymphoma both in vitro and in vivo." (PMID 32503630, 2020).
Immunodeficiency (6 papers, 2020 to 2024). Failure of the immune system to protect the body adequately from infection, due to the absence or insufficiency of some component process or substance. "RASGRP1 is a guanine-nucleotide exchange factor known to control key immune cell functions, and its reductions are associated with immunodeficiency and even life-threatening immune dysregulation." (PMID 34495251, 2021). "The other immunodeficiency is caused by mutations in the guanine nucleotide exchange factor RasGRP1, downstream of PLCγ1 signaling." (PMID 32251475, 2020). "Finally, an investigation performed to identify genome wide genetic variation associated with SCZ enriched for association with RA, one of the most severe immune system diseases, has indicated RasGRP1 as a strong link between genetic risk for SCZ and this autoimmune condition." (PMID 35204828, 2022). "In keeping with this, the RasGRP1 gene has been recently indicated by genome wide investigation as a point of risk convergence between SCZ and immune system diseases." (PMID 35204828, 2022). "The first area is its role in lymphocyte homeostasis, which can be summarized by the identification of loss-of-function RasGRP1 mutants in two patients with ALPS, one patient with immunodeficiency, and three patients with EBV-associated lymphoproliferative disease." (PMID 36675167, 2023). "RASGRP1 is an important guanine nucleotide exchange factor and activator of the RAS-MAPK pathway following T-cell antigen receptor (TCR) signaling, and its deficiency causes immunodeficiency with impaired cytoskeletal dynamics." (PMID 37026010, 2023). "Additionally, compelling investigations have indicated RasGRP1 as a key molecule involved in peripheral immune processes of relevance to pathophysiology of severe immune diseases, including RA." (PMID 35204828, 2022).